CASZ1 (castor zinc finger 1)
Diseases named in the same sentence as CASZ1 in open-access papers (continued):
Sharing a sentence is not in itself a finding about the gene and the disease.
glioma (7 papers, 2022 to 2025). A benign or malignant brain and spinal cord tumor that arises from glial cells (astrocytes, oligodendrocytes, ependymal cells). "Univariate and multivariate Cox analyses confirmed CASZ1 as a risk factor, potentially serving as a novel prognostic biomarker for gliomas." (PMID 36276925, 2022). "The overexpression of CASZ1 protein may be caused by the low methylation abundance of the CASZ1 gene, which was also considered a potential marker for glioma patient prognosis." (PMID 36276925, 2022). "The Kaplan–Meier analysis was performed to determine whether CASZ1 methylation was associated with the prognosis of patients with gliomas." (PMID 36276925, 2022). "Tumor-infiltrating immune cells are strongly associated with tumorigenesis and progression; for instance, the transcription factor CASZ1 was significantly upregulated in gliomas and was related to EMT signaling." (PMID 40679044, 2025). "Conversely, contrary to the that reported by several previous studies, high CASZ1 expression has been observed in glioma tissues, where it functions as an oncogene by regulating the transcription of its target gene p75NTR." (PMID 38053207, 2023). "Conversely, CASZ1 is highly expressed in glioma and EOC, suggesting a tissue- and tumor-specific expression pattern." (PMID 38053207, 2023). "Using the microarray‐based analysis, we previously demonstrated that the transcription factor CASZ1 was significantly upregulated in gliomas." (PMID 36276925, 2022). "For the first time, we identified that the mRNA and protein levels of CASZ1 were significantly upregulated in glioma cells." (PMID 36276925, 2022). "First, we analyzed two external GEO datasets, GSE22867 and GSE50923, and found that the methylation level of the CASZ1 gene in glioma was remarkably decreased compared with normal brain tissue." (PMID 36276925, 2022). "Using our own glioma specimens, we consistently observed significant correlations between CASZ1 protein expression and Ki‐67 and vimentin expression by IHC." (PMID 36276925, 2022). "We have determined the effect of the CASZ1/p75NTR signaling axis on the malignant biological behavior of glioma cells." (PMID 36276925, 2022). "We show that CASZ1 expression is significantly elevated in gliomas, and it contributes to the malignant properties of glioma cells through promoting the transcription process of p75NTR gene." (PMID 36276925, 2022). "The CASZ1/p75NTR signaling axis is vital in the development and progression of glioma, being a novel potential target for glioma therapy." (PMID 36276925, 2022). "Nevertheless, the expression pattern and functional mechanism of CASZ1 are seldom explored in gliomas." (PMID 36276925, 2022). "CASZ1 overexpressed is inversely correlated with the unfavorable prognosis of glioma patients, which was confirmed as a new predictive indicator." (PMID 36276925, 2022). "We further explored the molecular mechanism by which highly expressed CASZ1 promoted the malignant behaviors of glioma." (PMID 36276925, 2022). "In summary, this study reports that CASZ1 is overexpressed in gliomas, and is inversely correlated with the unfavorable prognosis of glioma patients, which was confirmed as a new predictive indicator." (PMID 36276925, 2022). "To determine the correlation between CASZ1 methylation and clinicopathological features, we screened 139 cases of non‐recurrent glioma from the CGGA glioma database with methylation data." (PMID 36276925, 2022). "Our findings indicate that highly expressed CASZ1 in glioma cells acts as a pro‐oncogene factor in gliomas via regulating transcriptional process of target gene p75NTR, which was identified as an unfavorable prognostic marker in patients with gliomas." (PMID 36276925, 2022). "Herein, CASZ1 was identified as a novel potential oncogene in glioma tissues from GEO and TCGA datasets." (PMID 36276925, 2022).
glioma (continued). "Furthermore, our study did not include various important molecular factors such as IDH status, autophagy-related genes, hsa-miR-196a-5p, and transcription factors like CASZ1 as predictors for glioma prognosis." (PMID 37296207, 2023). "However, the expression trend of CASZ1 varies in different solid tumors, exhibiting upregulation in glioma tissues and epithelial ovarian cancer (EOC) cells." (PMID 38053207, 2023). "CASZ1 was highly expressed in glioma tissues, predicting poor prognosis in glioma patients." (PMID 36276925, 2022). "Conversely, knocking down p75NTR could rescue the invasion abilities of glioma cells, which were promoted by overexpressed CASZ1 gene." (PMID 36276925, 2022). "This as well explains the upregulated CASZ1 mRNA and protein levels in gliomas." (PMID 36276925, 2022). "Next, the biological role of CASZ1 overexpression in gliomas was investigated." (PMID 36276925, 2022). "In gliomas with high CASZ1 expression, we found a restricted infiltration level but upregulated chemokines, including CXCL16, CCL22, CCL25, and CXCL2, which could attract DCs and T cells." (PMID 36276925, 2022). "CASZ1 overexpression had significant effects on tumorigenesis and progression of glioma cells." (PMID 36276925, 2022). "Our study indicated that CASZ1 might be a potential prognostic biomarker and a therapeutic target for gliomas." (PMID 36276925, 2022). "However, we found that the overexpression of CASZ1 promoted glioma cells initiation and progression via activating the transcription of p75NTR gene." (PMID 36276925, 2022). "We demonstrate that CASZ1 expression is elevated in glioma tissues and cells." (PMID 36276925, 2022). "We focused on the role, mechanism, and prognostic value of CASZ1 in glioma cells." (PMID 36276925, 2022). "CASZ1 is expected to become a novel target for the treatment of gliomas." (PMID 36276925, 2022). "CASZ1 is hypomethylated in gliomas, and its status is negatively correlated with CASZ1 mRNA level." (PMID 36276925, 2022). "And upregulated CASZ1 promoted the malignant properties of gliomas." (PMID 36276925, 2022). "Additionally, CASZ1 is positively related to immune cell infiltration and expression of proinflammatory interleukins or chemokines, which establish a microenvironment that probably promotes cancerous properties and glioma progression." (PMID 37509718, 2023). "Similarly, this study demonstrated that CASZ1 expression might be regulated by DNA methylation, and higher methylation levels were related to a better outcome in glioma patients." (PMID 36276925, 2022). "Besides, CASZ1 expression was related to levels of immune infiltration and chemokines in gliomas." (PMID 36276925, 2022). "Similarly, the upregulation of CASZ1 could promote cell invasion, whereas knockdown of which could suppress glioma cell invasion." (PMID 36276925, 2022). "CASZ1 also enhances the proliferation and invasion of glioma cells by directly upregulating NGFR (i.e., p75NTR), which is considered an oncogene for glioma." (PMID 37509718, 2023). "Within the 422 glioma cases included in the CGGA cohort, CASZ1 expression increased in glioma tissues with 1p/19q non‐codeletion, wild‐type IDH, and high grade groups." (PMID 36276925, 2022). "Our study found low methylation level of the CASZ1 gene in glioma and an evident negative correlation between methylation level and expression." (PMID 36276925, 2022). "We observed that CASZ1 mRNA expression was overexpressed in gliomas compared to normal brain tissues." (PMID 36276925, 2022).
dilated cardiomyopathy (6 papers, 2017 to 2026). Cardiomyopathy which is characterized by dilation and contractile dysfunction of the left and right ventricles. "A patient with dilated cardiomyopathy was found carrying a point mutation (p.Lys351X), which lies in a conserved region of CASZ1, causing truncation from the 350th amino acid that impairs its transcription-activating ability." (PMID 37509718, 2023). "CASZ1 has been confirmed to interact with T-box transcription factor 20 (TBX20), and double haploinsufficiency of both genes induced dilated cardiomyopathy and cardiac fibrosis in mice." (PMID 37509718, 2023).
cardiomyopathy (5 papers, 2017 to 2026). A disease of the heart muscle or myocardium proper. "CASZ1 is also involved in 1p36 deletion syndrome, which is characterized with dysmorphic facial features, intellectual disability, developmental delay, hearing loss, seizures, cardiomyopathy, and cardiovascular malformations." (PMID 37795486, 2023). "Since CASZ1 plays a crucial role in heart morphogenesis, it is reasonable that loss-of-function mutations could lead to cardiomyopathy or congenital heart diseases (CHD) with structural defects, as were observed in CASZ1-depleted mice or Xenopus." (PMID 37509718, 2023). "Some other genes may be responsible for cardiomyopathy as PDPN, and CASZ1." (PMID 36369750, 2023).
congenital heart disease (5 papers, 2017 to 2023). "CASZ1 mutations and the association with congenital heart diseases." (PMID 37509718, 2023). "IGF2BP3 and CASZ1 have key functions in cardiac development, since defects in these genes lead to congenital heart disease." (PMID 34895303, 2021). "We would envision these findings are not restricted to TBX20 and CASZ1 but rather are applicable to other genes and other forms of congenital heart disease (CHD) and DCM, and predict that genome sequencing of familial CHD will ultimately reveal a spectrum of additional CHD susceptibility alleles." (PMID 28945738, 2017).
esophageal cancer (5 papers, 2018 to 2023). A primary or metastatic malignant neoplasm involving the esophagus. "In urothelial carcinomas, cervical carcinomas, and oral squamous cell carcinomas, various types of CASZ1 mutations were observed, while in esophageal cancer and prostate cancer, CASZ1 was found to be hypermethylated or silenced by miRNA, respectively, and therefore decreased in expression." (PMID 37509718, 2023). "Similarly, CASZ1 downregulation has been observed in colorectal cancer, esophageal cancer, lung adenocarcinoma, and clear cell renal cell carcinoma, where it has been associated with patient prognosis and could serve as a novel prognostic marker." (PMID 38053207, 2023). "Hypermethylation of CASZ1, CDH13 and ING2 genes detected using cell-free DNA in blood samples can be applied as a potential biomarker for the diagnosis of esophageal cancer." (PMID 30355852, 2018). "Hypermethylation of CASZ1, CDH13 and ING2 detected in plasma cell-free DNA can be applied as a potential noninvasive biomarker for diagnosis of esophageal cancer." (PMID 30355852, 2018).
cervical carcinoma (4 papers, 2019 to 2023). A carcinoma arising from either the exocervical squamous epithelium or the endocervical glandular epithelium. "A clinical case report showed human papillomavirus DNA integration into the CASZ1 gene locus in a patient with cervical cancer, which disrupted CASZ1 gene expression." (PMID 38053207, 2023).
Stroke (4 papers, 2023 to 2024). Sudden impairment of blood flow to a part of the brain due to occlusion or rupture of an artery to the brain. "CASZ1 was previously associated with cardiovascular traits, including blood pressure, stroke, and rHTN34,35." (PMID 38851835, 2024). "The association between CASZ1 gene variants and stroke risk in Chinese population studies have shown that CASZ1 genetic variants rs4845941 and rs778228 are significantly associated with an increased risk of stroke." (PMID 38053207, 2023). "Gender-stratified analysis also shows that CASZ1 rs778228 locus is associated with a higher risk of stroke in females." (PMID 38053207, 2023). "CASZ1 and its related genes may promote the occurrence of stroke, which is of great significance for the treatment and prevention of stroke." (PMID 38053207, 2023).
Candida infection (3 papers, 2018 to 2025). "The loss of CASZ1 during mucosal Candida infection significantly impaired Th17 and regulatory T cell (Treg) responses, consequently diminishing the mice’s ability to clear the secondary infection." (PMID 40868317, 2025). "Loss of Casz1 in the context of mucosal Candida infection severely impairs Th17 and Treg responses, and lowers the ability of the mice to clear the secondary infection." (PMID 29467767, 2018). "Furthermore, the loss of Casz1 results in the severe impairment of Th17 and Treg responses during mucosal Candida infection, rendering mice deficient in Casz1 less capable of clearing secondary infections." (PMID 38053207, 2023). "We next examined the role of Casz1 during oral Candida infection, a model in which IL-17A and Th17 cells are required for anti-fungal defense in the host." (PMID 29467767, 2018).
clear cell renal cell carcinoma (3 papers, 2019 to 2024). "Similarly, CASZ1 exhibits downregulation in esophageal carcinoma, lung adenocarcinoma, and clear cell renal cell carcinoma, where expression levels correlate with patient prognosis." (PMID 38053207, 2023).
colorectal cancer (3 papers, 2020 to 2023). A primary or metastatic malignant neoplasm that affects the colon or rectum. "Furthermore, a CASZ1–MASP2 fusion transcript, detected in colorectal cancer, encodes an N-terminally truncated MASP2 controlled by the CASZ1 promoter." (PMID 38053207, 2023).
experimental autoimmune encephalomyelitis (3 papers, 2018 to 2025). An autoimmune demyelinating disease of the central nervous system that is produced experimentally in animals by the injection of homogenized brain or spinal cord in Freund's adjuvant. "Casz1 deficiency in CD4+ T cells lowers susceptibility to experimental autoimmune encephalomyelitis, consistent with the reduced frequency of Th17 cells, despite an increase in Th1 cells in mice." (PMID 29467767, 2018). "The absence of CASZ1 in CD4+ T cells reduced susceptibility to experimental autoimmune encephalomyelitis." (PMID 40868317, 2025). "In both in vitro and in vivo settings, Casz1 plays a vital role in Th differentiation, as evidenced by the reduced susceptibility of CD4+ T cells lacking Casz1 to experimental autoimmune encephalomyelitis." (PMID 38053207, 2023).
Left ventricular noncompaction cardiomyopathy (3 papers, 2019 to 2023). Left ventricular non-compaction (LVNC) is characterized by prominent left ventricular trabeculae and deep inter-trabecular recesses. "Additionally, a novel variant of the CASZ1 gene, c.2443_2459delGTGGGCACCCCCAGCCT (p.Val815Profs*14), was identified in a patient with DCM and left ventricular noncompaction cardiomyopathy (LVNC), highlighting the role of CASZ1 as a pathogenic gene for human LVNC." (PMID 38053207, 2023).
lung adenocarcinoma (3 papers, 2023 to 2024). A carcinoma that arises from the lung and is characterized by the presence of malignant glandular epithelial cells. "Furthermore, in lung adenocarcinoma and idiopathic pulmonary fibrosis, CASZ1 shows hypermethylation and low expression, which is significantly associated with the prognosis of lung adenocarcinoma." (PMID 38053207, 2023). "A recent study found that CASZ1 promoted EMT and metastasis of lung adenocarcinoma (LUAD) by directly binding to two sites on the promoter of the integrin subunit αV (ITGAV) gene, thereby upregulating its expression." (PMID 37509718, 2023).
Varicose veins (3 papers, 2019 to 2025). Enlarged and tortuous veins. "Taken together, our data supports the proposition that rs11121615 is a causal variant influencing risk of developing varicose veins via alterations in the transcription factor CASZ1, an upstream regulator of vascular structure." (PMID 31570750, 2019).
ventricular septal defect (3 papers, 2019 to 2023). The presence of a defect (opening) in the septum that separates the two ventricles of the heart. "A CASZ1 missense mutation p.L38P has been identified in a family with congenital ventricular septal defect (VSD), and a CASZ1 nonsense mutation p.K351X has been identified to be associated with DCM." (PMID 31268246, 2019). "It has been reported that CASZ1 loss‐of‐function mutation contributes to familial DCM and congenital ventricular septal defect (VSD)." (PMID 31268246, 2019). "Moreover, a missense mutation in a non-essential region that impairs CASZ1 transcriptional activity has been found in patients with ventricular septal defect (VSD), similar to one phenotype of CASZ1-depleted mice." (PMID 37509718, 2023).
Arrhythmia (2 papers, 2019 to 2023). Any cardiac rhythm other than the normal sinus rhythm. "Patient 76654, a girl with hypoplastic bulbus oculi whose mother had arrhythmias and whose sister died at age 9 because of a pontine glioma carried the maternally inherited deletion in 1p36.22, encompassing among others the CASZ1 and MTOR genes." (PMID 37012328, 2023).
epithelial ovarian cancer (2 papers, 2018 to 2022). "In contrast, the knockdown of CASZ1 led to opposing effects, consistent with the findings in ovarian cancer." (PMID 36276925, 2022). "In contrast, CASZ1 is highly expressed and responsible for cell migration and invasion in epithelial ovarian cancer, which indicated CASZ1 had different expression patterns and functions in various human cancers." (PMID 29506567, 2018).
lung carcinoma (2 papers, 2023 to 2025). "Recent studies have shown that CASZ1 also plays an oncogenic role in lung cancer, with its expression positively correlated with cancer metastasis and poor prognosis." (PMID 38053207, 2023). "Specifically, CASZ1 regulates ITGAV expression, promoting lung cancer migration, invasion, and epithelial–mesenchymal transition." (PMID 38053207, 2023).
osteoarthritis (2 papers, 2021 to 2023). A noninflammatory degenerative joint disease occurring chiefly in older persons, characterized by degeneration of the articular cartilage, hypertrophy of bone at the margins and changes in the synovial membrane. "Since CASZ1 functions in Th17 cell production, and immune modulations of osteoarthritis, it is possible to propose a regulatory effect on both innate and adaptive immunity during other pathogenic processes." (PMID 37509718, 2023). "According to a recent study, CASZ1 plays an anti-inflammatory role in osteoarthritis by downregulating interleukin 6 (IL-6) and tumor necrosis factor-alpha (TNF-α), while preventing apoptosis of chondrocytes, which are unable to regenerate." (PMID 37509718, 2023). "However, whether CASZ1 is differentially expressed in an osteoarthritis environment is still unclear." (PMID 37509718, 2023).
primary aldosteronism (2 papers, 2023). An endocrine disorder characterized by excessive production of aldosterone by the adrenal glands. "In a recent GWAS study on primary aldosteronism, CASZ1 was identified as a gene associated with this condition, and the overexpression of CASZ1 inhibited aldosterone biosynthesis in adrenal cells." (PMID 38053207, 2023).
rhabdomyosarcoma (2 papers, 2020 to 2022). A rare aggressive malignant mesenchymal neoplasm arising from skeletal muscle. "The CASZ1 p.Arg25Cys variant was recently found in an embryonic rhabdomyosarcoma tumor." (PMID 35737725, 2022).
asthma (1 paper, 2017). "Epigenomic studies have identified methylation patterns specific to COPD (e.g., C10orf11 in lung), asthma (e.g., IL13, RUNX3, TIGIT in PBMCs) and IPF (e.g., CASZ1 in lung), although much work remains to characterize cell-specific changes and include more ARDS and PAH samples." (PMID 28774304, 2017).